EGFR (epidermal growth factor receptor)
Diseases named in the same sentence as EGFR in open-access papers (continued):
Sharing a sentence is not in itself a finding about the gene and the disease.
tumor (continued). "Using nude mouse xenograft models of erlotinib-resistant human NSCLC NCI-H1975 harboring EGFR L858R/T790M double mutation, mefatinib demonstrated similar or even better anti-tumor activity as compared with afatinib at the same dose." (PMID 34719670, 2021). "The loss of EGFR T790M suggests the emergence of alternative mechanisms of acquired resistance, as the result of a more heterogeneous tumor with a more aggressive phenotype." (PMID 33922215, 2021). "NSCLC tumors bearing EGFR exon 19 deletion was found to have a lower tumor mutation burden compared with the EGFR L858R subtype despite similar smoking history." (PMID 34113560, 2021). "Despite good results in PF cell pellets, other studies suggest that NGS on body fluid supernatants possesses higher performance for detecting EGFR mutations in cfDNA compared to body fluid sedimentary tumor cells and plasma cfDNA specimens." (PMID 34199799, 2021). "The current limitations of anti-EGFR therapies by Cetuximab or other drugs likely relate to the mutation status and activation of the EGFR pathway in the patients’ tumour cells." (PMID 34944837, 2021). "The EphB4 status in carcinoma cells was positively correlated with tumor size, T factor, and Ki-67 labeling index in all patients and was associated with poor relapse-free survival in EGFR mutation-positive patients." (PMID 34445227, 2021). "Further, the dual analysis of EV-derived cargo has the potential to go beyond monitoring and be used in lieu of a tumor biopsy for non-invasive screening for both sensitizing and resistance mutations in EGFR across a patient’s treatment course." (PMID 34692681, 2021). "Mutation and overexpression of EGFR is associated with a number of tumours including breast, lung, colorectal, ovary and prostate." (PMID 34771633, 2021). "The BENEFIT trial, for example, observed that patients with only common EGFR mutations had significantly longer mPFS than those possessing concurrent tumor-suppressor genes or other driver oncogene alterations." (PMID 34513661, 2021). "LB performed at different post-operative times can quantify the circulating tumor DNA and/or identify the presence of mutations in EGFR, which can point to recurrence or tumor progression." (PMID 34440926, 2021). "Since overexpression and hyperactivation of EGFR is often found in NF1-associated MPNST tumor tissues and cells, we examined the expression level of pEGFR by IHC." (PMID 34948100, 2021). "In our study, the prevalence of EGFR mutation in tumor cells was 45.55%, ALK rearrangement 8.11%, ROS-1 rearrangement 2.56%, which was similar to the results of other studies 23-25." (PMID 33859531, 2021). "Increased EGFR expression was associated with a high malignancy grade, a poor clinical stage and large tumor size." (PMID 34679042, 2021). "Follow-up of post-operative patients with an LB can be envisaged to monitor a combination of the quantification of the circulating tumor free DNA and examination for mutations in EGFR as well as other associated genomic alterations." (PMID 34440926, 2021). "For example, increased core α1-6-fucosylation of EGFR was associated with increased dimerization and phosphorylation, which resulted in increased EGFR-mediated signalling associated with tumour cell growth and malignancy." (PMID 33671245, 2021). "The population of the study consists of 158 tumor samples, which were received for analysis of EGFR mutations, 20 samples with a small sample size were excluded." (PMID 33639678, 2021). "In a Phase I/II study, it was found to have an overall response rate (ORR) of 57.9% with a disease control rate of 89.5% in patients who had progression of disease on first or second-generation EGFR TKI with a defined tumor T790M mutation status." (PMID 34238332, 2021). "Epidermal growth factor receptor (EGFR) protein overexpression is seen in the majority of HGGs and is implicated in tumor cell migration and aggressiveness 15-17." (PMID 34158840, 2021).
tumor (continued). "The mutation rates of EGFR for the groups with tumor cell number ≤500 and > 500 were 40.7% (11/27) and 43.8% (119/272) respectively, without significant difference (P=0.764)." (PMID 34034456, 2021). "In this study, we showed that the SPP1 expression is significantly higher in LUAD tumor tissues and in patients with EGFR mutation." (PMID 34178613, 2021). "We showed in two patients that VAF of EGFR mutations in ctDNA is concordant with tumor volume changes." (PMID 34680416, 2021). "Alternatively, the weighted pooled estimate of loss of an EGFR mutation in patients with detected mutations in the primary tumor was 7% (95% CI 4–10%)." (PMID 35201504, 2021). "Despite preclinical efficacy, the success of wtEGFR targeting mAbs cetuximab and panitumumab has been associated with on-target, off-tumor toxicity in other tumor types, due to their significant binding to EGFR expressed on normal tissues." (PMID 34568006, 2021). "For example, cancers harboring translocations that form fusion transcripts, such as BCR-ABL, or mutations, such as BRAF or EGFR, depend on these gene products’ activity for tumor maintenance." (PMID 34211974, 2021). "Epidermal growth factor receptor (EGFR) activation through tumour EGFR gene mutations drives malignancy in a proportion of patients with NSCLC." (PMID 33648453, 2021). "Computed tomography (CT) imaging presents a perspective of the entire tumor and its microenvironment, allowing prediction of the EGFR mutation status globally." (PMID 34422624, 2021). "This paradoxical mechanism of tumor progression upon β-catenin deficiency has been partly elucidated by establishing the connection between the adherent junction complex and EGFR signaling in HCC." (PMID 34633987, 2021). "Except for higher consistency of EGFR mutation in tumor tissue and CTCs preparations, they also pointed out that the concordances of exon 19 and exon 21 were significantly different (96% and 55%, respectively)." (PMID 35049681, 2021). "To confirm that the block in tumour formation was caused by loss of EGFR palmitoylation we expressed the palmitoylation-defective EGFRC1025A mutant in the same mouse model." (PMID 34610265, 2021). "Our study found that MET genomic alterations were statistically related to age and tumor stage and co-existed with mutations of other oncogenic driver genes, such as EGFR and BRAF." (PMID 34660325, 2021). "Another problem is the heterogeneity of mutations in primary tumours and metastatic lesions, especially EGFR and KRAS, with the misclassification rate ranging from 0 to 45%." (PMID 33602172, 2021). "Among the 22 patients, we identified EGFR mutations that matched to tumor tissues in 14 of fraction 6 samples and 10 of platelet-poor plasma samples." (PMID 34178690, 2021). "Elucidation of the mechanisms underlying EGFR-mediated tumor immune escape and the development of effective immune therapeutics are urgently needed." (PMID 33537094, 2021). "EGFR kinase domain mutations were identified in 61.3% of the tumours (57 of 93; 95% CI, 0.512 to 0.714)." (PMID 34804960, 2021). "When tumor tissue is limited, a ctDNA assay can be used to identify certain genomic mutations, including EGFR." (PMID 34977873, 2021). "Overexpression or increased activation of ADAM17 in tumor cells has been associated with the initiation and progression of carcinomas, especially when EGFR is activated." (PMID 34771725, 2021). "EGFR 19Del mutations were more frequent in tumours with CTR ranging from 0.25 to 0.5 (71.4%, 5/7) than in those with CTR ranging from 0.5 to 1 (41.2%, 7/17) and from 0 to 0.25 (20.0%, 6/30) (P=0.022)." (PMID 34804960, 2021). "EGFR overexpression and mutation have been described as an oncogenic driver in several tumor types including HNSCC, making it a promising target for anticancer therapies in the last decade." (PMID 34257586, 2021).
tumor (continued). "In fact, several studies reported that EGFR mutated NSCLC appeared to have intra-tumor heterogeneity on contrast enhanced (CE) CT images and hazy areas in tumor regions which cause low-intensity holes on the CT images." (PMID 33428651, 2021). "Microvesicles isolated from plasma of NSCLC patients can be used for EGFR genotyping for the detection of drug-resistance mutations, demonstrating improved concordance with tumor tissue compared to a conventional ctDNA." (PMID 34178690, 2021). "Our findings suggest that the presence of LncRNA H19 SNP rs217727 is related to the EGFR mutation in LADC patients, and the LncRNA H19 SNP rs217727 and rs2107425 are associated with progressed tumor status for LADC patients with EGFR wild-type." (PMID 33799753, 2021). "It is reasonable to conclude that the tumor response rate was better correlated with the MFs of TKI‐sensitizing EGFR mutations determined in the earlier phases of treatment, that is, at C4 vs. C9." (PMID 33131198, 2021). "The FLAURA phase 3 trial of osimertinib vs gefitinib in first line also showed a shorter PFS and OS in EGFR‐mutant NSCLC harboring the L858R mutation in tumor tissue." (PMID 33969622, 2021). "EGFR TKIs have been reported to cause immunogenic apoptosis of tumor cells, and subsequently releasing aberrant intracellular antigens and recruiting T cells via interferon-γ-induced major histocompatibility complex class I presentation." (PMID 34113560, 2021). "The 38 samples from patients tested in tumor tissue for EGFR-activating mutations included 29 samples from EGFR-mutant and 9 from EGFR wild-type patients." (PMID 34680416, 2021). "The in vitro study of Chang on the HCC827 NSCLC cell line expressing mutated EGFR, suggested that the combination of gefitinib and zoledronic acid caused more tumor suppression." (PMID 34201833, 2021). "EGFR amplification or mutation facilitates tumor proliferation, invasion, migration and apoptosis inhibition by regulating multiple downstream cascades, and EGFR inhibitors provide an effective therapeutic target for EGFR-mediated cancer." (PMID 33758622, 2021). "In this regard, CTCs from the CSF of patients with LM from EGFR-mutated or ALK-rearranged NSCLC have a highly concordant molecular profile (89.5%) with a paired primary tumor." (PMID 34207653, 2021). "Significantly downregulated expression of miR-122 associated with EGFR gene mutation has been reported in a study assessing plasma and surgically-resected tumour tissues from male Japanese smokers with AC52." (PMID 33658555, 2021). "High expression of SLUG in primary HNSCC was a marker for reduced disease-free survival and was linked to tumor recurrence and the expression of EGFR." (PMID 34771518, 2021). "Vice versa, the patient tumor sample harbored an EGFR mutation (c.2361G > A; VAF: 30.5%) that was lost in the PDX." (PMID 34362423, 2021). "Since a CT tumor size ≥ 29 mm is a potential predictive factor for sputum cytology positive, sputum should be collected in such cases for the EGFR mutation analysis." (PMID 33757469, 2021). "In this regard, a significant tumour suppression associated with a prolonged survival was shown in athymic nude mice bearing EGFR-positive human TNBCs treated with cetuximab-IR700 and exposed to NIR-light (50 J/cm2 on day 1 and 100 J/cm2 on day 2)." (PMID 33836238, 2021). "The secretion of tumor growth factor (TGF‐α), Epidermal growth factors(EGF) by tumor cells, and upregulation of epidermal growth factor receptors‐like (EGFR, FGFR‐3) are implicated in the pathogenesis of TP and MAN." (PMID 33074559, 2021). "Preclinical studies demonstrated PD-L1 overexpression by EGFR-mutated tumor cells as a mechanism of immune escape." (PMID 34634633, 2021). "Genetic analysis of circulating tumor DNA in blood revealed EGFR T790M mutation (abundance 2%) and EGFR 19-del mutation (abundance 1%)." (PMID 33578601, 2021).
tumor (continued). "Recent reports have described the therapeutic effect of BAY-293 in EGFR-mutated tumor cell lines, and also its synergistic action with Osimertinib and KRASG12C inhibitors." (PMID 34205562, 2021). "The higher TMB in EGFR-mutant SCC indicated that EGFR driver mutations had a great impact on mutation number of tumor cells, although they belonged to a same disease subtype in pathology." (PMID 34195081, 2021). "Significantly, a truncal EGFR-activating mutation (R108K) was identified in the primary tumor and was also found to be maintained in the mCRPC samples and in a PDX model." (PMID 34568716, 2021). "Since the region of the vocal box is constantly under stress for sound production, the EGFR and related tissue growth was specifically evaluated in a study associated with neoplasms during squamous cells carcinogenesis." (PMID 34943184, 2021). "The epidermal growth factor receptor (EGFR) is often expressed on the surface of several different cancers and has been implicated in the progression of such tumor cells." (PMID 34769444, 2021). "At the single‐patient level, we detected variegated tumor heterogeneity dynamics supported by combinations of driver EGFR mutations." (PMID 33942501, 2021). "In most of these studies, patients whose tumor harbored oncogenic alterations (particularly EGFR mutations and ALK and ROS1 rearrangement) were excluded." (PMID 34208111, 2021). "Recently, disturbances in the tumor microenvironment caused by EGFR antibody have also been recognized as factors in treatment failure." (PMID 33632198, 2021). "By far the largest fraction of the current molecular data on SR was generated indirectly by analyzing the emergence of mutated circulating tumor DNA (ctDNA) in the blood of CRC patients under anti-EGFR treatment." (PMID 34271981, 2021). "The prevalence of EGFR mutation in tumor cell was 45.55%, ALK rearrangement 8.11%, ROS-1 rearrangement 2.56%, PD-L1 expression positive 59.01%." (PMID 33859531, 2021). "It was said that EGFR mutation in patients with SCC was caused by tumor heterogeneity and the component of mixed adenocarcinoma, especially in small biopsy specimens." (PMID 33869057, 2021). "In this study, the types of EGFRm were completely concordant between the tumor DNA and ctDNA when both were positive for an EGFR activating mutation." (PMID 33270375, 2021). "The aim of this study was to investigate the reasonable timing of radiotherapy for stage IV non-small-cell lung cancer (NSCLC) with EGFR-positive mutations during targeted therapy based on tumour volume change (TVC)." (PMID 34631535, 2021). "EGFR activating mutations are known to be strong tumor drivers, but in addition to EGFR mutations, a diversity of genomic profiles has been reported recently on the basis of multi‐region whole‐exome sequencing." (PMID 33982444, 2021). "Other studies have shown that ADAM12 is associated with the EGFR signaling pathway and mediates tumor progression through interactions with other factors." (PMID 34604068, 2021). "Genomic studies in almost all types of human tumors show aberrations in several RTKs associated with tumor development and progression such as EGFR, HER2/ErbB2, MET, etc.." (PMID 33918490, 2021). "Our findings are in agreement with these observations, since the expression of EMT markers in tumor spheres was associated with a higher resistance to erlotinib and irreversible EGFR inhibitors." (PMID 33922104, 2021). "Detection and quantification of EGFR mutations in circulating tumor DNA using the highly sensitive BEAMing method should greatly assist in optimizing treatment decisions for advanced NSCLC patients." (PMID 34296539, 2021).
tumor (continued). "EGFR expression is highly enriched in UC tissues and strongly associated with certain tumor grades and stages as well as risk of recurrence." (PMID 34868059, 2021). "Given the co-occurrence of wtEGFR amplification seen with EGFR mutations and splice variants, the cross-reactive EGFR-targeting 806 scFv should provide greater tumor cell coverage, resulting in better tumor control." (PMID 34568006, 2021). "Since patients with positive EGFR protein expression are more likely to benefit from EGFR-targeted fluorescence imaging, the focus herein was to identify patient characteristics or tumor features associated with positive EGFR protein expression." (PMID 33707521, 2021). "Depatux-M comprises a tumor-specific epidermal growth factor receptor (EGFR) targeting antibody (Depatux, formerly mAb806) linked to the cytotoxin monomethyl auristatin F (MMAF)." (PMID 34549181, 2021). "We further analyzed the association of LINE-1 methylation level with tumor stage, EGFR mutation status, adjusting for patients’ age and gender using multiple linear regression." (PMID 34403448, 2021). "The same study indicated 63 putative miRNA–mRNA interactions were potentially involved in EGFR-mutated tumor, including DUSP4 and MUC4 axes in EGFR-mutated LADC." (PMID 34830377, 2021). "Tumours harboured a higher ratio of EGFR G719X and S768I co-mutations, which were mutually exclusive of L858R and exon 19del." (PMID 33889543, 2021). "In both cases, MR features describing tumor textural heterogeneity and shape irregularity were linked to EGFR, suggesting increased diversity in EGFR-mutated and EGFR-amplified tumors." (PMID 34208595, 2021). "Tumor genotyping with the peptide nucleic acid‐locked nucleic acid (PNA‐LNA) PCR clamp method revealed a secondary mutation of EGFR T790M in addition to the primary EGFR L858R mutation." (PMID 33471376, 2021). "Overexpression or somatic mutation of EGFR causes the aberrant activation of its tyrosine kinase and the dysregulation of its downstream signals that contribute to the tumor growth and progression and the poor prognosis of NSCLC patients." (PMID 34155348, 2021). "AKT has many upstream signals, among which EGF/EGFR is one signal that is closely associated with tumor progression." (PMID 34069970, 2021). "The detection of EGFR mutations in tumor-tissue samples is considered the gold standard for molecular diagnostics." (PMID 34680416, 2021). "With this product, CAR-T cells are directed to the tumor due to the specificity of the EGFRvIII mutation, secrete a BiTE that can target tumor cells expressing normal EGFR through tumor heterogeneity or antigen loss." (PMID 33874996, 2021). "Dysregulation of EGFR caused by mutation, amplification, and overexpression plays a key role in tumor progression of NF1-MPNST." (PMID 34948100, 2021). "Concurrently, NGS testing of both tumor tissue and blood specimens again identified EGFR exon 21 L858R point mutation, and EGFR T790 M mutation was only found in blood specimens and Met amplification was only found in tumor tissue specimens." (PMID 34397683, 2021). "Although tumours including abundant tumour ratio involved only two lesions (right S6 and left S8), EGFR mutations were clinically examined in all lesions." (PMID 33707471, 2021). "LM occurred and EGFR C797S/exon 19 deletion (19del) mutations was detected by next-generation sequencing (NGS) of CSF circulating tumor DNA (ctDNA)." (PMID 34871271, 2021). "To test higher ctDNA content in a plasma fraction, we compared mutation detection rate between the plasma fraction and whole plasma in 22 NSCLC patients with known EGFR mutations in tumor tissues." (PMID 34178690, 2021). "Endocan enhances tumor growth driven by mutated EGFR by facilitating EGFR signaling through direct binding and enhancing the EGF-EGFR interaction." (PMID 34976811, 2021). "We also assessed the association between PD-L1 membranous staining on tumor cells using 1% cut-off and the presence of the EGFR and KRAS mutations." (PMID 33956842, 2021).